YY1 (YY1 transcription factor)
Diseases named in the same sentence as YY1 in open-access papers (continued):
Sharing a sentence is not in itself a finding about the gene and the disease.
cancer (continued). "YY1 is positively correlated with more malignant phenotype and poorer outcome in several human cancer types." (PMID 31703732, 2019). "It has been demonstrated that NF-κB/Snail/YY1/RKIP circuitry is involved in the EMT development of cancer cells." (PMID 31703732, 2019). "Cancer tissues (T) exhibited a higher YY1 protein expression, whereas miR-500a-5p expression was reduced compared with the corresponding non-cancerous controls (N)." (PMID 30737378, 2019). "In spite of these studies, positive correlation between YY1 mRNA and protein levels has also been previously reported in other cancers." (PMID 29564133, 2018). "YY1 has been suggested to have an essential role in multiple types of cancers, which was mainly due to its elevated expression levels in cancers and its functional role in promoting cell proliferation." (PMID 29098080, 2017). "We recently found that CP2c directly interacts with another TF, YY1, which is also overexpressed in multiple cancers, including HCC." (PMID 28412749, 2017). "To explore the influence of YY1 and ROS on cancer cell invasiveness, we found that shYY1 and DPI suppressed the A549 cell invasiveness induced by MCT-1; thus, the combinatory effect (shYY1+DPI) strongly prohibited cancer cell invasion." (PMID 28394354, 2017). "It has fundamental roles in embryogenesis, cell proliferation, and differentiation, which strongly suggests a potentially important function for YY1 during cancer development and progression." (PMID 29052509, 2017). "Overexpression of YY1 has been observed in various cancers, including prostate cancer, ovarian cancer, and colon cancer." (PMID 28412749, 2017). "Because YY1 is overexpressed in many cancers, YY1 is considered to be a potential novel prognostic marker and therapeutic target." (PMID 28412749, 2017). "Like CP2c, YY1 is a ubiquitously expressed TF involved in diverse biological processes, such as embryogenesis, differentiation, proliferation, and cancer progression." (PMID 28412749, 2017). "YY1 shares many properties with cancer stem cells (CSCs) that drive tumorigenesis, metastasis and drug resistance and are regulated by overexpression of certain transcription factors, including SOX2, OCT4 (POU5F1), BMI1 and NANOG." (PMID 27225481, 2016). "Hyperactivation of NF-κB in cancer cells transcriptionally activates the expression of Snail and Yin Yang 1 (YY1), and YY1 can also upregulate Snail." (PMID 26716415, 2016). "YY1 frequency of expression was associated with the SOX2, BMI1 and OCT4 frequency of expression across many cancers, though the type of association varied." (PMID 27225481, 2016). "Studies have repeatedly showed that in the majority of the tumors studied, YY1 transcript levels are significantly higher than in the relative normal counterparts for each cancer type analyzed." (PMID 26104682, 2015). "One of the outstanding transcription factors that we have identified is Ying Yang 1(YY1), which plays an important role in divergent biologic processes such as embryogenesis, differentiation, cellular proliferation and cancer progression." (PMID 25885449, 2015). "Clearly, the overall activity mediated by PDT-induced NO or the addition of exogenous NO resulted, in part, in the interference of a dysregulated loop (the pro-survival/anti-apoptotic/NF-κB/Snail/YY1/RKIP) found to be present in many cancers." (PMID 26319434, 2015). "Accordingly, abnormal YY1 protein levels have been shown to affect the clinical behavior of several cancer types." (PMID 26104682, 2015).
cancer (continued). "The findings revealed that NO mediates its effects by interfering with a dysregulated pro-survival/anti-apoptotic NF-κB/Snail/YY1/RKIP loop which is often expressed in cancer cells." (PMID 26319434, 2015). "Reported studies implicated the role of the high level of NO in its interference with the dysregulation of NF-κB/Snail/YY1/RKIP in cancer cells." (PMID 26319434, 2015). "We established the dysregulation of the NF-κB/Snail/YY1/RKIP loop in cancer cells and demonstrated its role in the regulation of EMT." (PMID 25053986, 2014). "The results demonstrated that in a long period of hypoxic condition, YY1 silenced cell lines suppressed the colonization and proliferation of cancer cells in the lungs." (PMID 25053986, 2014). "Bonavida and Baritaki have investigated the role of YY1 in the initiation and development of cancer metastasis." (PMID 25053986, 2014). "For example, increased YY1 expression was observed in cancers of the prostate, ovary, colon, breast, bone, liver, lung, bladder, cervix and blood." (PMID 24884523, 2014). "The transcription factor YY1 is expressed in normal tissues and is upregulated in various types of cancer, including PCa, with positive and negative regulatory effects on gene expression." (PMID 25174820, 2014). "Noteworthy, recent interest has shifted due to YY1 level of expression and its various functions in different cancers." (PMID 25053986, 2014). "Yin Yang-1 (YY1) is an NF-κB regulated gene, which is hyperexpressed in several cancers and is known to function as a transcriptional activator or a repressor depending on its interacting partners and the promoter context (." (PMID 23874387, 2013). "YY1 protein levels have been shown to be deregulated during tumorigenesis and elevated YY1 levels have been detected in many types of cancers." (PMID 23226345, 2012). "Our recent data showed that transcript levels of the transcription factor YY1 are higher in several cancer types including melanoma when compared with those of normal tissue." (PMID 22929570, 2012). "Genes for which we know little about, like LRIG2, but associated with poor prognosis of different cancer types, have been detected by our method to correlate with the expression of three TFs (FOSTAF1 and YY1) across blood cell groups." (PMID 22721266, 2012). "Due to the critical role that the transcription factor YY1 plays in the life of mammalian cells, and its link to cancer, there is an urgent need for a better understanding of its regulation." (PMID 21253604, 2011). "In a similar line, it is important to emphasize the fact that the unusually high levels of YY1 protein are often observed in normal and cancer cells." (PMID 19712462, 2009). "We predict the differential expression of several transcription regulator genes (including HSF2, ARNT, MEF2A, ATF2 and YY1) that are strongly related to the cancer grade." (PMID 20025723, 2009). "Previous studies indicated that BAP1 might inhibit cancer cell growth by interacting with one or more partner proteins, including YY1, RBBP7, HCF-1, H2A, ASXL1/2, and FoxK1/K2." (PMID 40688406, 2025). "A number of studies have shown that YY1 plays crucial roles in cancer drug resistance." (PMID 40867514, 2025). "Conversely, in cancer, tumors may exploit both proteins: YY1 can promote immune evasion by upregulating immune checkpoint molecules (e.g., PD-L1), while RKIP downregulation may enhance pro-survival pathways." (PMID 41459495, 2025). "However, in HPV-positive cancer cells, increased YY1 levels displaced TFAP2, alleviating repression." (PMID 40953061, 2025). "We concluded that RTK/MAPK inhibition downregulated YY1 in diverse oncogene-addicted cancer models." (PMID 39604408, 2024).
cancer (continued). "YY1 regulates embryonic development, hematopoiesis and cancer development." (PMID 38739758, 2024). "Additionally, YY1 can promote the proliferation and metastasis of GC via multiple cancer-related pathways." (PMID 38347631, 2024). "Furthermore, YY1 has been shown to both promote and inhibit angiogenesis in different types of cancers." (PMID 39796650, 2024). "In cancer cells, YY1’s impact extends to the regulation of key anti-apoptotic genes, including Bcl-2, Bcl-xl, Mcl-1, and survivin, known for their involvement in therapeutic resistance and cancer progression." (PMID 38893192, 2024). "Furthermore, numerous studies have demonstrated a significant correlation between YY1 expression and poor prognosis, drug resistance, as well as cancer metastasis." (PMID 38347631, 2024). "In addition to its regulation of PD-L1, YY1 has several other anti-cancer activities, such as the regulation of proliferation and cell viability, invasion, epithelial–mesenchymal transition (EMT), metastasis, and chemo-immuno-resistance." (PMID 38539569, 2024). "They found that NADPH oxidase 4 (NOX4) and YY1 expressions were positively linked to acquired resistance to EGFR-TKIs, while PD-L1, a downstream NOX4 target, ultimately contributed to immune escape in cancer cells." (PMID 38539569, 2024). "However, it has also been found that YY1 is overexpressed in many types of cancers, specifically in several metastatic cancers." (PMID 38539569, 2024). "YY1 is key to understanding the progression of EMT in cancer." (PMID 39796650, 2024). "Furthermore, YY1 can inhibit apoptosis through several mechanisms, contributing to cancer cell survival and chemoresistance." (PMID 38539569, 2024). "unconcealed that ferroptosis is important in T cell-induced cancer cell death and that HnRNP L promotes cancer immune escape in part by targeting the YY1/programmed death ligand-1(PD-L1) axis and inhibiting ferroptosis in castration-resistant prostate cancer (CRPC) cells." (PMID 36845720, 2023). "Thus, as a multifunctional regulator possessing significant biological functions, YY1 has the potential to be a key regulator of cancer development." (PMID 37724907, 2023). "Similarly, we believe there exists another indirect relationship between RKIP and PTEN via the dysregulated NF-κB/Snail/YY1 loop expressed in cancer." (PMID 37205308, 2023). "Yin Yang 1 (YY1) is a well-known transcription factor that controls the expression of many genes and plays an important role in the occurrence and development of various cancers." (PMID 37240065, 2023). "Overall, our study provides new evidence that the cross-talk between RKIP and YY1 might be an important regulator of cancer progression and drug resistance, with potential clinical implications." (PMID 37894300, 2023). "Therefore, it is crucial to meticulously explore YY1 protein structure and the dynamic alteration of its interactome in each cancer type." (PMID 36880159, 2023). "YY1 is a zinc finger structural protein belonging to the human GLIKruppel family of nuclear protein, which functions as a transcriptional activator or repressor in a variety of cancers." (PMID 37828612, 2023). "Together, these findings suggest that a cross-talk between RKIP and YY1 might play a crucial role in cancer progression and drug resistance." (PMID 37894300, 2023).
cancer (continued). "YY1 can either promote or inhibit target gene expression, depending on its interaction partners, and it is also the primary driver behind the epigenetic network in cancer." (PMID 37724907, 2023). "YY1 plays dual biological roles in the initiation and progression of various cancers." (PMID 37081988, 2023). "Therefore, YY1 is an attractive drug target for cancer models through preventing DNA binding in order to reduce YY1 expression." (PMID 37686541, 2023). "We found a strong inducing effect of YY1 expression in the cell cycle (31%), apoptosis (16%), and DNA damage (16%) pathways across different cancers, as well as a potent inhibitory effect on the RASMAPK (19%), EMT (12%), hormone ER (12%), and RTK (12%) pathways." (PMID 37894300, 2023). "It has been detected that YY1 was highly expressed in a variety of cancer types including CRC." (PMID 36880159, 2023). "In contrast, targeting YY1 directly, through small interfering RNAs (siRNAs), gene editing or small molecule inhibitors, can be therapeutically more effective and generalized in YY1-overexpressed resistant cancers." (PMID 37686541, 2023). "Furthermore, the role of YY1 in regulating cancer cell stemness was investigated using the sphere formation assay, which revealed that YY1 overexpression increased the number and volume of LNCaP cells, while YY1 knockout had a significant inhibitory effect." (PMID 37771187, 2023). "Although the CP2c mRNA was upregulated in cancer tissues over that in the adjacent normal tissues, its level was low in YY1 high cancers, which is consistent with previous reports that YY1 directly interacts with CP2c and suppresses the transcriptional activity of CP2c." (PMID 37444605, 2023). "Examining the interactions of YY1 and these anti-apoptotic genes may further illustrate their role in cancer pathology and may prove to be beneficial for future targeting strategies." (PMID 37686541, 2023). "Inhibition of YY1 could partially regulate the sensitivity of human prostate PC-3 cancer cells to TRAIL mediated apoptosis induced by chemotherapeutic drugs." (PMID 37828612, 2023). "The expression of YY1 in cancer is regulated through various cancer factors and signaling pathways." (PMID 37686541, 2023). "Importantly, the CP2c protein expression in cancer tissues was significantly higher in patients with YY1 low compared to YY1 high." (PMID 37444605, 2023). "Further studies found that YY1 could weaken the expression of downstream cancer suppressor PTEN by up-regulating the expression level of lncRNA Kcnq1ot1, thus promoting the adverse progression of TNBC." (PMID 37901333, 2023). "First, we explored the YY1 and PEBP1 gene mutation rate in pan-cancer." (PMID 37894300, 2023). "Finally, we collected the IC50 of various drugs across different cancer cell lines from the GDSC and CTRP databases and associated them with the corresponding YY1 and PEBP1 mRNA levels." (PMID 37894300, 2023). "The review summarizes the knowledge regarding the role of YY1 in viral life cycle and cancer." (PMID 35408813, 2022). "Hence, by using the data from TCGA, CPTAC, and GEO, we performed a pan-cancer analysis of YY1 gene in a total of 33 different tumors, and the results suggested that the mechanism of YY1 action was different in various tumors." (PMID 35791393, 2022). "The transcription factor YY1 has been studied in many cancers." (PMID 35719931, 2022). "Future prospective studies of YY1 expression and immune cell infiltration in different cancer populations may help to shed more light on the problem's mechanisms." (PMID 35791393, 2022). "In cancer cells, YY1 might inhibit RKIP gene expression indirectly, through Snail positive regulation." (PMID 35205667, 2022). "In addition, the genes significantly associated to OS were enriched for targets of several key cancer TFs like ELK1, YY1 and RUNX3." (PMID 36584096, 2022). "EZH2 is an essential partner of YY1 in promoting cancer cell progression." (PMID 35406384, 2022).
cancer (continued). "Increasing evidence suggests that YY1 can promote the development and progression of many cancers." (PMID 35811688, 2022). "The results showed that YY1 expression differed from the prognosis of various cancers." (PMID 35791393, 2022). "Accumulating evidence indicates that YY1 is involved in cancer progression." (PMID 35811688, 2022). "YY1 regulates various cancer-related genes and activates key oncoproteins." (PMID 35406384, 2022). "Furthermore, we confirmed that de novo methylation is precluded across cancers at CpGs lying in genomic regions enriched for TF binding signatures associated with SP1, CTCF, NRF1, GABPA, KLF9, and/or YY1." (PMID 35440061, 2022). "YY1 has been known to work as an oncogene in cancer and one of its main the transcriptional targets in LC may be the immune-enhancer and tumor-suppressor RKIP." (PMID 35205667, 2022). "mRNA expressions of YY1 were remarkably correlated with cancer stages." (PMID 35359580, 2022). "Several studies have identified a role for YY1 in diseases including cancer." (PMID 35693944, 2022). "The role of YY1 in regulating DNA methylation has undoubtedly been proven in various cancers." (PMID 35408813, 2022). "The correlation between expression levels of YY1 and Sox2 was observed among all cancer types." (PMID 35719931, 2022). "YY1 is a zinc finger protein involved in transcriptional control in human cancers." (PMID 34535152, 2021). "Moreover, as a transcription factor, YY1 can transcriptionally regulate the expression of lncRNAs in cancer cells." (PMID 34863279, 2021). "Yin Yang 1 (YY1) is a transcription factor playing a dual role in cancer." (PMID 34445183, 2021). "YY1 is a known indirect inhibitor of MYC involved in cancer development." (PMID 33502086, 2021). "In addition, YY1 regulates the expression of many cancer-related genes such as MYC (alias c-myc) and c-Fos." (PMID 34063990, 2021). "For example, we suppose that retinoid receptors, MAX and GATA3, as demonstrated in other types of cancer, could interact with the zinc finger protein YY1 that is known to modify chromatin structure and interact with insulators elements such as CTCF." (PMID 34449674, 2021). "Indeed, Myc (Myc proto-oncogene), STAT3, NF-κB, YY1 (Yin Yang 1), and AP-1 (activator protein 1) were found to bind the promoter and positively regulate PD-L1 expression in cancer cells." (PMID 34503236, 2021). "Indeed, the involvement of YY1 in cancer development and progression depends on different genetic and epigenetic factors able to modulate its expression." (PMID 34445183, 2021). "Notably, YY1 and Oct4 protein levels strongly correlated with each other in all analyzed cancer types." (PMID 33728560, 2021). "Furthermore, NO-mediated inhibition of the NFκB /Snail/Yin Yang 1 (YY1)/Raf-1 kinase inhibitor protein (RKIP) circuitry suppresses cancer cell resistance and metastasis." (PMID 34830916, 2021). "The YB1 transcription factor induces the stemness-related gene expression and epithelial-mesenchymal transition in hepatocellular carcinoma while YY1 is associated with transcription factor (SOX2, OCT4, BMI1) expression in cancers suggesting a co-regulatory role in cancer stem cells." (PMID 33453053, 2021). "Therefore, YY1 is conceptualized as an oncogenic protein fueling the emergence of lethal cancer phenotypes." (PMID 33728560, 2021). "In cancer, the expression levels or functions of YY1 are commonly altered." (PMID 33728560, 2021). "YY1 is a common transcription factor and is overexpressed in a variety of cancers." (PMID 34933678, 2021). "YY1 has been identified up‐regulated and functioned as an oncogene in several kind of cancers." (PMID 33675150, 2021).